SLC12A4 (solute carrier family 12 member 4)
Description:
Mediates electroneutral potassium-chloride cotransport when activated by cell swelling. May contribute to cell volume homeostasis in single cells. May be involved in the regulation of basolateral Cl(-) exit in NaCl absorbing epithelia (By similarity). [Isoform 4]: No transporter activity.
Synonyms: hKCC1; KCC1; CTC-479C5.17
Tractability: Small molecule: a structure with a bound ligand is known; it belongs to a druggable protein family. Antibody: UniProt places it where antibodies can reach, with high confidence; its Gene Ontology location is reachable by antibodies, with high confidence; UniProt predicts a signal peptide or a membrane-spanning region. PROTAC: ubiquitination databases record sites on it; its protein half-life has been measured.
Gene: Protein-coding gene on chromosome 16 (67,943,474 to 67,969,601, reverse strand). Ensembl gene ENSG00000124067.
Subcellular location: Cell membrane
Subcellular location (Human Protein Atlas): Cell Junctions; Nucleoplasm; Cytokinetic bridge; Primary cilium
Pathways (Reactome):
Transport of small molecules: Cation-coupled Chloride cotransporters
Gene Ontology:
Molecular function: ATP binding; potassium:chloride symporter activity; protein binding; chloride:monoatomic cation symporter activity; protein kinase binding; transmembrane transporter activity
Biological process: cell volume homeostasis; chloride ion homeostasis; chloride transmembrane transport; chloride transport; potassium ion homeostasis; potassium ion import across plasma membrane; potassium ion transmembrane transport; monoatomic ion transport; transmembrane transport
Cellular component: lysosomal membrane; apical plasma membrane; membrane; plasma membrane
Genetic constraint (gnomAD): Loss-of-function variants: 82 observed, 118.64 expected, observed/expected ratio (o/e) 0.69, 90% interval 0.58 to 0.83. The upper end of that interval is the gene's LOEUF score, 0.83, which puts it in group 3 of 6, group 1 being the genes least tolerant of losing a copy. Missense variants: 1,294 observed, 1,487.2 expected, observed/expected ratio (o/e) 0.87, 90% interval 0.83 to 0.91. Synonymous variants: 598 observed, 607.95 expected, observed/expected ratio (o/e) 0.98, 90% interval 0.92 to 1.05.
Homologues: Orthologues: chimpanzee SLC12A4 (99% identical), rabbit SLC12A4 (97% identical), guinea pig SLC12A4 (97% identical), pig SLC12A4 (96% identical), rat Slc12a4 (96% identical), mouse Slc12a4 (96% identical), dog SLC12A4 (96% identical), macaque SLC12A4 (94% identical), tropical clawed frog slc12a4 (82% identical), zebrafish slc12a4 (82% identical), Drosophila melanogaster kcc (55% identical), Caenorhabditis elegans kcc-2 (47% identical), and 4 more. Paralogues in human: SLC12A6 (76% identical), SLC12A7 (69% identical), SLC12A5 (69% identical), SLC12A1 (28% identical), SLC12A2 (27% identical), SLC12A3 (26% identical), SLC12A9 (24% identical), SLC12A8 (14% identical).
Diseases named in the same sentence as SLC12A4 in open-access papers:
SLC12A4 is named in the same sentence as 23 diseases in open-access papers, as found by Europe PMC text mining. Sharing a sentence is not in itself a finding about the gene and the disease. The quoted sentences say what the papers report.
Acidosis (1 paper, 2023). Abnormal acid accumulation or depletion of base. "Acidosis resulted in reduced expression of many genes encoding ion channels, including SLC12A4 encoding a potassium chloride cotransporter, sodium dependent phosphate carrier and many others." (PMID 37110207, 2023).
breast carcinoma (1 paper, 2023). "Dual targeting of SLC6A14 with SLC25A15, SLC12A4, SLC1A5 and SLC38A5 also reduced growth in MCF7 and MDA-MB-231 human breast cancer cell lines." (PMID 38066114, 2023).
breast invasive carcinoma (1 paper, 2023). "In breast invasive carcinoma no predictive value was observed by SLC6A14, SLC12A4 or SLC25A15 alone, but there was a nonsignificant trend for reduced survival in SLC6A14-high combined with SLC12A4-high or SLC25A15-high expression." (PMID 38066114, 2023).
colorectal cancer (1 paper, 2023). A primary or metastatic malignant neoplasm that affects the colon or rectum. "Dual targeting of SLC6A14 and either SLC25A15 or SLC12A4 diminishes serine uptake and growth of colorectal cancer cells in vitro and in vivo, particularly in cells with compromised de novo serine biosynthesis." (PMID 38066114, 2023).
extrapyramidal movement disorder (1 paper, 2025). "In a patient exhibiting recurrent bouts characterized by intestinal dysmotility, extrapyramidal movement disorder, and headaches from late infancy onwards, whole exome sequencing trio analysis revealed a de novo heterozygous nonsynonymous variant in SLC12A4 (c.3193G>A)." (PMID 41414942, 2025).
Hypertension (1 paper, 2017). The presence of chronic increased pressure in the systemic arterial system. "KCC3 and KCC1 are potassium chloride transporters encoded by SLC12A6 and SLC12A4 respectively with partially overlapping function, and KCC3 knockout mice exhibit hypertension." (PMID 28748545, 2017).
cancer (5 papers, 2019 to 2025). A tumor composed of atypical neoplastic, often pleomorphic cells that invade other tissues. "Our results show that dual targeting of SLC6A14 with SLC25A15 or SLC12A4 is detrimental to cancer cell proliferation, especially in the context of low de novo serine synthesis." (PMID 38066114, 2023). "As a proof of concept, we targeted loci in healthy donor DNA, including a highly variable hexanucleotide repeat in C9orf72, and four cancer-related genes with guide RNAs previously validated for PCR-free targeted sequencing (GSTP1, KRT19, GPX1, SLC12A4)." (PMID 33830997, 2021).
tumor (5 papers, 2020 to 2025). "Nineteen genes (44%) demonstrated loss or promoter silencing of the wildtype allele in at least one tumour, with six genes (SLC12A4, LOXL2, ZCCHC4, LLGL2, MIPOL1, SCYL3) demonstrating this in multiple samples." (PMID 39794353, 2025). "Nevertheless, in established serine synthesis-deficient tumor xenografts, acute silencing of SLC6A14/SLC12A4 and to a lesser degree SLC6A14/SLC25A15 reduced tumor growth and serine levels, despite a large proportion of DOX escapers." (PMID 38066114, 2023). "Conversely, among the four downregulated genes (KANK2, SGCA, SLC12A4, and MEIS1), higher expression correlated with better prognosis, suggesting their potential tumor-suppressive roles." (PMID 40525903, 2025). "Collectively these results suggest that in serine synthesis-deficient tumors, targeting SLC6A14 together with an ion exchanger/facilitator (SLC12A4) or a mitochondrial serine transporter (SLC25A15) can decrease serine uptake, leading to reduced tumor growth." (PMID 38066114, 2023). "Moreover, five genes, including the SLC12A4, SLIT3, GYPC, TSPAN4, CYYBRD1, CYB5R3, and FBLN5 were identified as co-expressed in the healthy and tumor tissue groups." (PMID 37365287, 2023).
SLC12A4 also shares sentences with these, for which no sentence is quoted: sickle cell anaemia (3 papers); cerebral malaria (2); anemia (1); colon adenocarcinoma (1); glioma (1); Hyperinsulinemia (1); Hyperkalemia (1); infection (1); Insulin resistance (1); lymphoma (1); malaria (1); myocardial infarction (1); Obesity (1); Sepsis (1); Thrombus (1).